CDX2 (caudal type homeobox 2)
Diseases named in the same sentence as CDX2 in open-access papers (continued):
Sharing a sentence is not in itself a finding about the gene and the disease.
tumor (continued). "CDX2—a biomarker associated with tumor differentiation—also holds significant clinical relevance in CRC management; it is typically expressed in healthy colon cells but is often absent in poorly differentiated CRCs, correlating with aggressive disease and poorer outcomes." (PMID 40507221, 2025). "In our case, no mutations in the BRAF gene were detected in the patient’s tumor samples, while CDX2 expression was confirmed, which supports the hypothesis about the correlation between CDX2 expression and the status of the BRAF gene." (PMID 39518386, 2024). "Low CDX2 staining was associated with poor differentiation and the presence of lymphovascular or perineural invasion and was more common in colon and right-sided tumours." (PMID 39201360, 2024). "Immunohistochemical detection of CDX2 expression is recognised as a clinically useful diagnostic biomarker in CRC specially in those metastatic cases where tumour origin is unknown." (PMID 38439814, 2024). "Loss of CDX2 function associates with oncogenesis, a property of tumour suppressor genes." (PMID 38439814, 2024). "Homeobox Transcription factor (CDX2) is one of three proteins encoded by the ParaHox gene cluster, playing a crucial developmental role in the digestive system of vertebrates and having a particular role as a tumour suppressor in the distal colon." (PMID 39516345, 2024). "Loss of CDX2 expression may disrupt these regulatory mechanisms, fostering tumor cell detachment from the primary site and facilitating their migration towards lymphatic vessels, thereby augmenting the likelihood of lymph node metastasis." (PMID 39328205, 2024). "There was a significant association between grade-3 tumours and loss of CDX2 expression." (PMID 38439814, 2024). "This is because CDX-2 plays a role in the proliferation and differentiation of CRC cell, and the downregulation of CDX-2 expression may lead to the loss of tumor differentiation." (PMID 37749564, 2023). "Our results support that loss of CDX2 is a marker of poorly differentiated tumours." (PMID 35027037, 2022). "Besides, we discovered that the levels of CDX2, E-cadherin, and N-cadherin had a remarkable association with tumor size, depth grading of tumor invasion, and lymph node status." (PMID 36277982, 2022). "CDX2 expression is inversely associated with tumor grade in CRC." (PMID 36186777, 2022). "We observed a loss of CDX2 expression in 6.6% of tumor buds, which differed from the tumor core." (PMID 36186777, 2022). "In addition, such Cdx1:Cdx2:APCMin compound mutants exhibit a highly penetrant villous tumor phenotype coincident with loss of EphrinB1 expression." (PMID 33525395, 2021). "The molecular mechanisms behind the enrichment of CDX2 loss in MSI-H tumours and rather benign (medullary CRC) or highly aggressive (MANEC/NEC) morphologic subtypes as well as in right-sided CRCs should be explored in further studies to potentially address potential therapeutic implications." (PMID 34616012, 2021). "Early‐stage patients not qualifying for chemotherapy might be reconsidered for such treatment if their tumor has loss of CDX2 and mutated BRAF." (PMID 29900672, 2018). "In addition to its diagnostic utility, CDX2 is reported to exert tumor-suppressor functions by controlling a number of genes involved in proliferation, migration, and carcinogenesis." (PMID 29682204, 2018). "Loss of CDX2 expression has been associated with poor tumor differentiation." (PMID 29155818, 2017).
tumor (continued). "The expression levels of CDX2, survivin, B-cell lymphoma 2 (Bcl-2), Bcl-2-associated X protein (Bax), cyclin D1, s-phase kinase-associated protein 2 (Skp2) and c-Myc in the tumor cells were analyzed by western blotting and semi-quantitative reverse transcription polymerase chain reaction." (PMID 25738600, 2015). "Association of Cdx2 loss in tumor and lymph nodes with clinicopathological features (n = 59)." (PMID 24130965, 2013). "CDX2 is expressed specifically in colonic and small intestinal mucosa and has been implicated in disorders involving abnormal intestinal differentiation and neoplasia." (PMID 23408490, 2013). "Indeed, only tumor location was linked to loss of Cdx2 expression, which occurs more frequently in the right-side of the colon (p = 0.0088)." (PMID 24130965, 2013). "Patient characteristics (n = 201) and association with Cdx2 expression in tumor." (PMID 24130965, 2013). "CDX2 represents the latest in a series of transcription factors that have found important applications in diagnostic surgical pathology as highly specific and sensitive markers of specific cell and tumor types." (PMID 22268990, 2012). "Furthermore, statistical analysis showed that CDX2 pCTC numbers were associated with tumour- node-metastasis stage and lymph node status." (PMID 21364588, 2011). "In addition a preliminary analysis of the relative expression of CDX2 alleles in tumour/normal tissue suggested some variation in the levels, however further analysis is required before any conclusions can be drawn." (PMID 11161380, 2001). "However, resistance emerged which was associated with CDX2 expression and tumor differentiation." (PMID 41620448, 2026). "However, whether loss of CDX2 expression plays a particularly active role in tumor progression in MSI/MMR-deficient tumors remains to be elucidated." (PMID 33823840, 2021). "Also, tumours with focal loss of CDX2 in the budding cells may represent a unique group with highly invasive potential." (PMID 30425348, 2018). "In addition, a region of the tumor showed obvious reduction or complete loss of Cdx2 staining." (PMID 29463648, 2018). "The capacity of loss of CDX2—a differentiation-inducing transcription factor—to cooperate with the BRAF mutant to promote intestinal cell transformation is not surprising since CDX2 abnormalities have been associated with BRAF-driven serrated tumor development." (PMID 29652830, 2018). "Although our primary hypothesis regarding the association between CRCs and CDX2 expression status was whether the alterations from CDX2-positive to CDX2-negative during tumor progression or chemotherapy were negligible, the investigation of the opposite situation also yields valuable information." (PMID 29682204, 2018). "Whether CDX2 expression is associated with tumour prognosis is worthy of further pursuit." (PMID 29179508, 2017). "Immunohistochemistry showed that cytokeratin 20 was partially positive and caudal type homeobox 2 was positive in approximately 50% of the tumor cells." (PMID 41630024, 2026). "The PDO cohort was limited in size but reflective of real-world diversity, capturing the interplay between tumor differentiation, CDX2 expression, and KRASmut status; larger cohorts and randomized clinical trials with RNA-seq endpoints is warranted." (PMID 41118768, 2025). "CDX2 is a commonly used marker to confirm a gastrointestinal origin, especially in the lower gastrointestinal tract, but can be expressed in any tumor along this tract or with an enteric histologic phenotype." (PMID 40443973, 2025). "TF motif enrichment analysis revealed loss of accessibility at sites that contained motifs for epithelial-specifying genes, including HNF4A and CDX2 in patients with HiSquam tumours." (PMID 40468074, 2025). "The change of SOX2 expression is also observed in the mucosa surrounding the tumor, suggesting that, similarly to CDX2 changes, SOX2 changes precede the development of cancer." (PMID 40149431, 2025).
tumor (continued). "Immunohistochemistry (IHC) for further characterization showed the tumor was positive for CDX2, CK20, and SATB2." (PMID 41328080, 2025). "We identify PRKAB1 as a key upstream node and show that PF-06409577, a clinically safe first-in-class agonist, triggers CDX2-restoration, cell-type specific differentiation, and anti-tumor responses." (PMID 41118768, 2025). "Promoter methylation of at least one HOX related gene (ALX4, CDX2 or HOPX) or ARID1A gene was detected in 83.08% (54/65) of tumor samples." (PMID 40002854, 2025). "Here we applied this method to identify targets that restore expression of CDX2, a caudal-related homeobox transcription factor (TF) and tumor suppressor." (PMID 41118768, 2025). "The primary aim of this study was to evaluate the associations between CDX2 and SATB2 expression and tumor-infiltrating immune cells in CRC." (PMID 39998677, 2025). "Cdx1 and Cdx2 mRNA were detectable in the colonic tumor organoids derived from Apc+/− mice but were expressed at significantly lower levels than those observed in normal colonic epithelium." (PMID 40399276, 2025). "In both cohorts, lower CDX2 and SATB2 expression levels were associated with proximal tumor location, high tumor grade, MMR deficiency, and BRAF V600E mutation (p < 0.001 for all)." (PMID 39998677, 2025). "The relatively specific expression of CDX2 in gastrointestinal tumors makes it a useful marker for distinguishing the primary site of the tumor." (PMID 40636692, 2025). "The CDX2 expression is regulated by a wide range of intracellular mediators, including the potential tumor suppressor miR-196b, and CDX2 expression has been identified as the transforming event in a murine AML model." (PMID 41002427, 2025). "On the other hand, this analysis revealed that FOXC2 OE in M cells led to a closed chromatin state at the CDx2 locus, a tumour suppressor gene frequently deleted in colon CSCs." (PMID 40764669, 2025). "CDX2 demonstrated diffuse nuclear positivity in nearly all tumor cells, confirming intestinal differentiation." (PMID 41310725, 2025). "Not only does SOX2 specify direct squamous maturation, but its expression also inhibits proliferation signals and tumor suppressor mechanisms that have been shown to be required for subsequent CDX2-mediated intestinalization of esophageal squamous epithelium." (PMID 40587339, 2025). "Our findings that CDX2-low tumors cluster with poor differentiation and higher T stage support its role as a marker of tumor aggressiveness." (PMID 41388313, 2025). "This hypermethylation can lead to transcriptional silencing of CDX2, reducing its expression and eliminating its protective role in tumor growth control." (PMID 40740242, 2025). "We need a more refined method to assess CDX2 expression that integrates both the proportion of tumor nuclei showing staining and the staining intensity." (PMID 41388313, 2025). "Utilizing the Fisher’s Exact test, we analyzed the correlation between the CDX2 expression categories and the categories of tumor differentiation patterns, uncovering a statistically significant correlation (p-value = 0.011)." (PMID 38786321, 2024). "We found that BLM tumors showed a higher level of Cdx2-expressing cells compared to Min tumors, which was confirmed by using tumor-derived organoids." (PMID 38893159, 2024). "Parent tumor tissue and PDOs both demonstrated nuclear CDX2 staining, alongside membranous CK20 staining." (PMID 38542253, 2024). "One report employed a score combining the intensity level and the percentage of tumour cells expressing CDX2, categorizing samples with low, intermediate and high expression levels." (PMID 38439814, 2024). "Because tumor stem cells of BLM tumors showed increased expression of Cdx2, we focused on CDX2 as a potential regulator of BLM tumor differentiation." (PMID 38893159, 2024).
tumor (continued). "Using in vitro organoid cultures, here we show that the transcriptional programs in proximal and distal colon stem cells are differentially regulated by Cdx2, which drives different dependencies for tumor development." (PMID 38360902, 2024). "This approach fails to capture the intratumoral variations and overlooks the significant implications that varying CDX2 intensity levels within the same tumor can have on clinical outcomes, thus undermining the accuracy of prognostic assessments." (PMID 38786321, 2024). "In our study, low CDX2 expression was observed more commonly in right-sided (11.7%) than left-sided tumours (6.0%), which was statistically significant." (PMID 39201360, 2024). "In a series of 44 patients from the United States, CDX2 positivity defined as nuclear staining in 25% or more of tumor cells was present in 59.1% of cases." (PMID 39768557, 2024). "In this study, CDX2 positivity was defined as moderate nuclear staining in at least 5% of tumor cells." (PMID 39768557, 2024). "In our study, we aim to analyze this CDX2 expression diversity among different cancer clones within the same tumor, and to devise a new scoring system that encapsulates this intratumoral heterogeneity." (PMID 38786321, 2024). "Developmental transcription factors, such as CDX2, are thus critical in maintaining tissue-location specific transcriptional programs that create tissue-type origin specific dependencies for tumor development." (PMID 38360902, 2024). "The median PFS in first-line therapy was significantly inferior for those with CDX2-negative (N = 23) compared to CDX2-positive (N = 282) tumours (8 versus 12 months; Mantel-Cox log-rank test, p = 0.023)." (PMID 38439814, 2024). "To address these limitations, we developed a new scoring system that accounts for the variability in the intensity level of CDX2 expression at the tumor level." (PMID 38786321, 2024). "The immunohistochemical analysis revealed that the tumor was positive for CDX2, consistent with a gastrointestinal origin; the specimen was negative for CK7, CK20, and PAX-8, ruling out other common adenocarcinoma subtypes." (PMID 39434934, 2024). "In terms of sidedness, the rate of low CDX2 expression was numerically higher in the right-sided tumours (11.7%) than the left-sided tumours (6.0%)." (PMID 39201360, 2024). "In IHC studies, 90–95% of tumor samples from patients with CRC have an increased expression of CDX2, which is considered a highly sensitive and specific diagnostic marker for adenocarcinomas of intestinal origin." (PMID 39518386, 2024). "We also identified additional potential regulators of BLM epithelial tumor differentiation such as CDX2 and NDRG1." (PMID 38893159, 2024). "In unadjusted analyses, median OS (p < 0.001) and median PFS (p < 0.05) were inferior for patients with CDX2-negative versus CDX2-positive tumours." (PMID 38439814, 2024). "The association of CDX2 mRNA levels with difference in 5-year DFS was evaluated and found to be significant (p = 0.003) for the 15 CDX2-negative tumour patients." (PMID 39516345, 2024). "An elevation was noted in the mRNA expression of H19 and CDX2 in tumor tissues of CSCs-EVs-treated mice, while CSCs-EVs-sh-H19 decreased their expression." (PMID 37005676, 2023). "The CDX2‐low subgroup had relatively lower tumor purity, and higher stromal score, immune score, and ESTIMATE score (all p < 0.05)." (PMID 37602699, 2023). "We found that CD8+ T cells, dendritic cells (DCs), natural killer (NK) cells, and tumor‐infiltrating lymphocytes (TIL) were more abundant in the CDX2‐low subgroup (all p < 0.01)." (PMID 37602699, 2023). "Collagen expressed by Masson’s staining is an important component of the tumor stroma, and cancer cells expressed by CDX-2 staining are an important component of the tumor body." (PMID 37749564, 2023).
tumor (continued). "According to our extensive literature research, we were the first to produce a regression model for CDX2 expression loss which showed that poor tumor differentiation and MLH1/PMS2 heterodimer deficiency are independent factors for CDX2 expression loss." (PMID 37325467, 2023). "Overall, 78 (77.2%) patients needed additional immunohistochemical staining, particularly for CgA, Syn, CDX2, and CK, to confirm the neuroendocrine origin of the tumors and to detect the primary tumor site in those considered occult at initial diagnosis." (PMID 37338723, 2023). "The expression of CDX2 was correlated with longer survival in patients, when the nuclear staining of tumour cells was over the 10% of malignant cells." (PMID 37504367, 2023). "Poor tumor differentiation and MLH1/PMS2 heterodimer deficiency have been identified as potential predictors for CDX2 expression loss." (PMID 37325467, 2023). "Conversely, the clinical and pathological revision of the case HCM-CSHL-0608-C17 concluded that the tumor had originated from the small intestine (CDX2+, siNET), had metastasized to the pancreas, and displayed a proliferation index of 3% (G2 tumor)." (PMID 37082125, 2023). "A group of scientists performed analyses of CK7, CK20, MUC1, and CDX2 in tumour tissues of patients." (PMID 37504367, 2023). "Only an extensive immunohistochemical investigation, including the markers CDX2, TTF-1 and ISLET-1, was shown to be significantly associated with the identification of a primary tumor site." (PMID 37686593, 2023). "The rate of CDX2 positive expression in the tumor sections with positive CD10 and MUC2 expression was significantly higher than that in sections with negative CD10 and MUC2 expression." (PMID 37602699, 2023). "In our study, the CDX2‐low subgroup had relatively lower tumor purity, higher stromal score, and ESTIMATE score." (PMID 37602699, 2023). "We also managed to produce a regression model for CDX2 expression and showed that poor tumor differentiation and MLH1/PMS2 heterodimer deficiency are independent factors for CDX2 expression loss." (PMID 37325467, 2023). "A patient’s medical history and immunohistochemical staining (such as CK20, CK7, and CDX-2) can aid in identifying the tumor origin of breast and vulvar metastases." (PMID 37483522, 2023). "CDX2 protein immunoexpression in tumor cells, as well as its correlation with several clinicopathological criteria, were investigated." (PMID 35463729, 2022). "Since original tumors were poorly differentiated, the expression of CDX2 was relatively low in all tumor samples and their derivatives." (PMID 35853873, 2022). "Our data revealed that enhancing CDX2 expression blocks tumor progression and retards liver metastasis in CRC." (PMID 35449124, 2022). "CDX2 is a tumor marker for primary GI origin, and DOG1 is a marker for GI stromal tumors, which were both negative in our patient, and it helped us rule out primary GI neoplasm." (PMID 35706725, 2022). "We observed a significant correlation between the age of patients and CDX2 expression in tumor cells (P=0.02)." (PMID 35463729, 2022). "We also found that CDX2 showed the lowest expression ratio in tumor tissues compared with normal tissues, which was verified by immunohistochemical staining." (PMID 35535692, 2022). "Both tumor inducer and tumor suppressor roles have been indicated for CDX2 and its downregulation is often associated with CRCs." (PMID 36217307, 2022). "Two PDO lines (653 and 557) showed no staining for the intestinal-specific transcription factor CDX2, matching their primary tumours." (PMID 35860583, 2022). "A prominent example is the SOX4–Axin2 network and the CDX2–Axin2 network, both of which are reported to inhibit the proliferation and tumor formation of cancer cells by suppressing Wnt/β-catenin signaling." (PMID 35625787, 2022). "Emerging evidence suggests the crucial role of CDX2 as a tumor suppressor during colorectal carcinogenesis." (PMID 36186777, 2022).